TTR (transthyretin)
Diseases named in the same sentence as TTR in open-access papers (continued):
Sharing a sentence is not in itself a finding about the gene and the disease.
familial amyloid polyneuropathy (219 papers, 2008 to 2026). "ATTRv amyloidosis involves more than 120 identified TTR mutations; the Val30Met mutation is the most prevalent globally, with notable endemic foci in Portugal, Brazil, Sweden, and Japan." (PMID 41492466, 2026). "The ambiguity of the case prompted genetic analysis, which revealed a rare homozygous p.Ala101Val (c.302C>T) variant in the TTR gene, leading to the diagnosis of hereditary ATTRv amyloidosis." (PMID 41756701, 2026). "After evaluating the amyloid-disrupting effects of PGL and its derivatives on V30M TTR fibrils associated with ATTRv amyloidosis, we next explored their potential therapeutic activity against age-related ATTRwt amyloidosis and AD." (PMID 41492466, 2026). "Y69H (p.Y89H) variant hereditary transthyretin (ATTRv) amyloidosis causes meningeal amyloidosis, with mutant TTR deposits localized to the leptomeninges and vitreous body." (PMID 40931533, 2025). "In this study, 46 TTR gene mutations were identified in 235 symptomatic ATTRv amyloidosis patients, including V30M, A19D, P24S, S50I, and T60A mutations." (PMID 40898332, 2025). "Conversely, ATTRv amyloidosis is caused by pathogenic variants in the TTR gene and represents the most common form of hereditary systemic amyloidosis." (PMID 40870008, 2025). "Clinical trials of siRNAs that reduce both normal and mutated transthyretin (TTR), causing TTR amyloidosis, reported attenuated progression not only of the associated peripheral neuropathy but also cardiomyopathy." (PMID 41378166, 2025). "Familial amyloid polyneuropathies (FAPs) are a group of hereditary, life-threatening multisystem disorders most commonly attributed to mutated transthyretin (TTR)." (PMID 40406766, 2025). "In individuals with symptoms of polyneuropathy, diagnosis of ATTRv amyloidosis typically is confirmed with a positive result on genetic testing for germline TTR mutations." (PMID 40433205, 2025). "Genetic testing for TTR gene variants is critical for the accurate diagnosis and management of ATTRv amyloidosis." (PMID 40804349, 2025). "In ATTRv amyloidosis patients, the varying proportions of normal and mutated TTR deposition in different tissues warrant further investigation to clarify these differences." (PMID 40093801, 2025). "Hereditary ATTR amyloidosis (ATTRv amyloidosis) associated with variant TTR has historically been an intractable disease." (PMID 40429804, 2025). "Penetrance, prognosis, and regional distribution in patients with ATTRv amyloidosis vary with different single amino acid mutations in TTR gene." (PMID 40093801, 2025). "Hereditary ATTR amyloidosis (ATTRv amyloidosis) arises when mutations in the TTR gene are present from birth, causing the liver to produce structurally abnormal TTR proteins tending to misfold (Ref 103)." (PMID 40160040, 2025). "According to the ACMG guidelines on secondary findings, RYR1 and TTR are associated with malignant hyperthermia and hereditary TTR amyloidosis, respectively." (PMID 41296379, 2025). "Hereditary transthyretin amyloidosis (ATTRv-amyloidosis) is a rare autosomal dominant genetic disease characterized by multiple point mutations in the transthyretin (TTR) gene." (PMID 40940654, 2025). "TTR encodes transthyretin, and pathogenic TTR variants are associated with the development of hereditary TTR amyloidosis." (PMID 38229148, 2024). "TTR mutations like V30M or age-driven misfolding and aggregation of wild-type TTR are involved in familial amyloid polyneuropathy (FAP) and senile systemic amyloidosis (SSR), respectively." (PMID 38338354, 2024). "The specific pathogenic TTR variant is a significant factor in the clinical variability of ATTRv amyloidosis." (PMID 38907862, 2024). "ATTRv amyloidosis is an autosomal dominant disease caused by pathogenic variants in the TTR gene, which is located on chromosome 18." (PMID 39458146, 2024).
familial amyloid polyneuropathy (continued). "The transition of transthyretin (TTR), from the native tetrameric state to a fibrillar non‐native state represents a fundamental pathogenic event of systemic TTR amyloidosis (ATTR) yet to define." (PMID 38380705, 2024). "The genotype of ATTRv amyloidosis significantly influences its clinical presentation, with over 140 known TTR variants showing diverse pathogenic effects." (PMID 38907862, 2024). "Patients with a diagnosis of ATTRv amyloidosis with a documented TTR variant and neuropathy (baseline NIS of 5–130), a PND score of IIIb, a Karnofsky Performance Status score of ≥ 60%, and adequate liver and renal function." (PMID 39286810, 2024). "ATTRv amyloidosis is caused by variants in the transthyretin (TTR) gene that destabilize the TTR protein, leading to systemic deposition of TTR amyloid fibrils and impairment mainly to the peripheral nerves, autonomic nervous system, and heart." (PMID 38241252, 2024). "Familial amyloid polyneuropathy is an autosomal dominant inherited disorder provoked by the mutation of transthyretin (TTR)." (PMID 37834818, 2023). "Historically, most of the animal models for ATTRv amyloidosis were transgenic mice expressing human TTR variants." (PMID 37830598, 2023). "In ATTRv amyloidosis, point variants in the TTR gene lead to destabilization and dissociation of TTR from its native tetrameric conformation, and subsequent aggregation as amyloid fibrils." (PMID 37740174, 2023). "Hereditary transthyretin amyloidosis (ATTRv amyloidosis) is a rare, but life-threatening protein misfolding disorder due to TTR gene mutations." (PMID 37014422, 2023). "Pathogenic mutations in the transthyretin (TTR) gene cause variant TTR amyloidosis (ATTRv), inherited in an autosomal dominant manner." (PMID 36772971, 2023). "In a series of 298 patients over 62 years of age with unexplained LVH and an initial diagnosis of HCM, testing for a TTR mutation revealed a 5% prevalence of ATTRv amyloidosis." (PMID 37901600, 2023). "In heterozygous individuals affected by ATTRv amyloidosis, both variant and wild-type TTR are found within amyloid deposits." (PMID 36555787, 2022). "In this study, the ThT assay and in vitro aggregation assay showed that V30M, a major variant of ATTRv amyloidosis, markedly enhanced TTR aggregation, even in the presence of EVs." (PMID 35402512, 2022). "In ATTRv amyloidosis, variants such as V30M in TTR destabilize the tetrameric structure and facilitate aggregation." (PMID 35402512, 2022). "At least 94 different mutations in the TTR gene have been associated with the development of ATTRv amyloidosis with cardiomyopathy." (PMID 36555787, 2022). "Familial amyloid polyneuropathy (FAP) caused by a genetic mutation in transthyretin (TTR) is an autosomal dominant hereditary disease." (PMID 35627273, 2022). "Genetic testing confirmed a Val30Met mutation of the TTR gene consistent with hereditary TTR amyloidosis (hATTR)." (PMID 35751086, 2022). "For example, V30M (also termed TTRV30M) is the most common hATTR variant that causes TTR familial amyloid polyneuropathy (ATTR-FAP)." (PMID 35393947, 2022). "Familial amyloid polyneuropathy caused due to excess deposition of transthyretin (TTR) in CNS and peripheral organs can be treated with Inotersen- an ASO and Patisiran-anti-TTR siRNA." (PMID 36110526, 2022). "In 1978 the Portuguese group led by Pedro Costa demonstrated that Familial Amyloid Polyneuropathy was caused by the protein transthyretin through a classical mechanism of autosomal dominant transmission." (PMID 35237660, 2022). "A striking example of a protein for which unfolding promotes aggregation is transthyretin (TTR), the aggregation of which is linked to familial amyloid polyneuropathy (FAP)." (PMID 36203800, 2022). "In hereditary ATTRv amyloidosis, TTR gene variant forms amyloid, which is deposited in multiple organs such as the peripheral nerves, gastrointestinal tract, heart, eyes, and kidneys." (PMID 35402512, 2022).
familial amyloid polyneuropathy (continued). "The presence of a destabilizing mutation in the TTR gene can lead to the development of a genetic disease termed variant ATTR amyloidosis (ATTRv amyloidosis), mainly affecting the peripheral and autonomous nervous system, the heart, or both." (PMID 36555787, 2022). "In hereditary transthyretin amyloidosis (ATTRv amyloidosis), genetic mutations on TTR proteins usually compromise their stability, causing TTR dissociation into dimers and monomers." (PMID 36311011, 2022). "Transthyretin-Related Familial Amyloid Polyneuropathy (TTR-FAP) is an adult-onset, neurodegenerative disease causing muscular weakness and other systemic issues." (PMID 35642200, 2022). "Hereditary (variant) transthyretin amyloidosis (ATTRv amyloidosis), which is caused by variants in the transthyretin (TTR) gene, leads to TTR amyloid deposits in multiple organs and various symptoms such as limb ataxia, muscle weakness, and cardiac failure." (PMID 35402512, 2022). "Inotersen (Tegsedi, FDA approval in October 2018) is used to treat familial amyloid polyneuropathy caused by the mutation in the transthyretin (TTR) gene." (PMID 33816449, 2021). "In patients with familial amyloid polyneuropathy (FAP) caused by transthyretin (TTR) mutations, TTR fibrils form in the CNS and peripheral organs." (PMID 33996898, 2021). "Hereditary Transthyretin-Related Amyloidosis, a clinically heterogeneous autosomal dominant disease caused by pathogenic variants in the TTR gene, is characterized by the deposition of insoluble misfolded protein fibrils." (PMID 34658264, 2021). "AHSG is associated with alopecia-mental retardation syndrome 1, patients of familial amyloid polyneuropathy (FAP) carrying TTR Met30 mutation, and fibrinogen gamma chain (FGG) appear to be protected after ischemic stroke." (PMID 34168538, 2021). "ATTRv amyloidosis has an autosomal-dominant mode of transmission because of a point mutation of the TTR gene." (PMID 31907599, 2021). "Liver transplantation was established as a treatment for ATTRv amyloidosis in the 1990s to prevent the production of the variant TTR from the liver." (PMID 34361762, 2021). "For example, senile systemic amyloidosis is known to be caused by spontaneous aggregation of TTR, whereas familial amyloid polyneuropathy (FAP) and familial amyloid cardiomyopathy (FAC) are caused by genetic mutations in TTR." (PMID 33922648, 2021). "Used in AKCEA-TTR-LRx, a GalNac-ASO also designed to inhibit production of TTR, this technology is now being tested in phase three clinical trial in patients with polyneuropathy caused by hereditary TTR amyloidosis with positive results." (PMID 33996898, 2021). "For example, senile systemic amyloidosis is caused by the spontaneous aggregation of wild-type (WT) TTR, while familial amyloid polyneuropathy or familial amyloid cardiomyopathy is attributed to genetic modifications of TTR." (PMID 33800546, 2021). "Familial amyloid polyneuropathy (FAP) is a neurodegenerative disorder whose major hallmark is the deposition of mutated transthyretin (TTR) in the form of amyloid fibrils in the peripheral nervous system (PNS)." (PMID 32788615, 2020). "Transthyretin familial amyloid polyneuropathy (TTR-FAP) is an autosomal dominant disease caused by mutations in the TTR gene." (PMID 32493526, 2020). "ATTRv amyloidosis is due to missense mutations that make the transthyretin (TTR) tetramer unstable, and then, a misfolded variant of TTR protein aggregates, generating amyloid fibrils, which are found as protein deposits in tissues." (PMID 33316911, 2020). "The most frequent and severe forms of the disease are hereditary and associated with amino acid substitutions in the protein due to single point mutations in the TTR gene (ATTRv amyloidosis)." (PMID 33362465, 2020). "Of note were four African American carriers of TTR rs76992529 associated with amyloidogenic transthyretin amyloidosis, otherwise known as familial transthyretin amyloidosis (FTA)." (PMID 31797629, 2020).
familial amyloid polyneuropathy (continued). "Hereditary transthyretin (TTR) amyloidosis (ATTRv amyloidosis), which is caused by mutations in the TTR gene, is an inherited systemic disorder characterized by extracellular amyloid deposits." (PMID 31133063, 2019). "Hereditary transthyretin amyloidosis (ATTRv amyloidosis) is caused by a variant transthyretin (TTR), which is a serum protein secreted by the liver." (PMID 31133063, 2019). "Ala97Ser (A97S) is the major transthyretin (TTR) mutation in Taiwanese patients of familial amyloid polyneuropathy (FAP), characterized by a late‐onset but rapidly deteriorated neuropathy." (PMID 31502419, 2019). "Accumulation of variant TTR precipitates familial TTR amyloidosis, such as familial amyloidosis cardiomyopathy (TTR-FAC), familial amyloidotic polyneuropathy (TTR-FAP), and central nervous system selective amyloidosis (CNSA)." (PMID 30934952, 2019). "The use of doxycycline as an orphan drug for systemic amyloidosis caused by mutated TTR (Treatment of familial amyloid polyneuropathy." (PMID 31546787, 2019). "Liver transplantation has been established as a treatment for ATTRv amyloidosis patients, particularly for early-onset patients, from the viewpoint of halting the production of variant TTR by the liver." (PMID 30764529, 2019). "Familial amyloid polyneuropathy is a hereditary systemic amyloidosis caused by a mutation in the transthyretin (TTR) gene." (PMID 30552363, 2018). "Familial amyloid polyneuropathy (FAP) is a genetic disease leading to the production of a variant transthyretin (TTR) or a beta variant β2-microglobulin." (PMID 30161158, 2018). "Familial amyloid polyneuropathy (FAP) is a genetic systemic disease usually due to mutations of the transthyretin (TTR) gene (TTR-FAP) and sometimes to beta variant β2-microglobulin." (PMID 30161158, 2018). "The presence of extracellular deposits of amyloid aggregates of WT or L55P TTR, respectively, is a key hallmark of two pathological conditions, known as senile systemic amyloidosis and familial amyloid polyneuropathy." (PMID 30131519, 2018). "Using our structuralized protocol, we found one participant (1%) that had Fabry disease and three participants that had familial amyloid polyneuropathy (dominantly inherited transthyretin (TTR) mutations) presenting as DSPSFN." (PMID 28957343, 2017). "Fabry disease (1%) and familial amyloid polyneuropathy (3%) with Ala97Ser transthyretin (TTR) mutations were also detected." (PMID 28957343, 2017). "Recently, an in vitro study demonstrated that Schwann cells can contribute to neurodegeneration in TTR amyloidosis through the local expression of mutated TTR." (PMID 28335735, 2017). "Through systematic computational prioritization, we identified a missense mutation c.G148T in TTR gene which results in a p.V50L substitution known to cause transthyretin-related familial amyloid polyneuropathy." (PMID 27212199, 2016). "Familial amyloid polyneuropathy (FAP) is caused by mutations of the transthyretin (TTR) gene, predominantly expressed in the liver." (PMID 27584576, 2016). "Amyloid formation of the plasma protein transthyretin (TTR) has been linked to familial amyloid polyneuropathy and senile systemic amyloidosis." (PMID 27050398, 2016). "Familial amyloid polyneuropathy (FAP) is a neurodegenerative disease caused by deposition of mutated transthyretin (TTR)-derived amyloid fibrils in several organs." (PMID 27695122, 2016). "Familial amyloid polyneuropathy (FAP) caused by a mutation in transthyretin (TTR) gene is an autosomal dominant inherited disorder." (PMID 26529114, 2015). "Familial amyloid polyneuropathy (FAP) caused by mutations of transthyretin (TTR) is the most common cause of FAP, which is a multisystem disorder with autosomal dominant transmission." (PMID 26529114, 2015). "The extremely rare S52P TTR variant is the least stable TTR variant and causes the most aggressive phenotype of hereditary systemic TTR amyloidosis." (PMID 26286619, 2015).
familial amyloid polyneuropathy (continued). "A 37-year-old Portuguese Caucasian man with Val30Met transthyretin-related familial amyloid polyneuropathy presented with rapidly progressing visual loss in his left eye." (PMID 25282612, 2014). "The hereditary form is caused by transthyretin (TTR) gene mutations and is sometimes referred to as familial amyloid polyneuropathy (FAP) or familial amyloid cardiomyopathy (FAC)." (PMID 24767411, 2014). "Transthyretin-associated familial amyloid polyneuropathy (TTR-FAP) is a life-threatening disease transmitted as an autosomal dominant trait." (PMID 24572009, 2014). "Transthyretin familial amyloid polyneuropathy (TTR-FAP) is an autosomal dominant disorder caused by TTR gene mutations that destabilize the tetrameric transthyretin (TTR) protein, leading to tetramer dissociation, monomer misfolding, and aggregation." (PMID 23974642, 2013). "Current techniques for performing sequence analysis of TTR, the only gene known to be associated with TTR amyloidosis, detect >99% of disease-causing mutations." (PMID 23425518, 2013). "TTR, when mutated, is associated to another amyloidotic disorder, Familial Amyloid Polyneuropathy (FAP), characterized by the extracellular deposition of TTR in several organs with a special emphasis in the peripheral nerve." (PMID 23028965, 2012). "Transthyretin associated amyloidosis (Familial amyloid polyneuropathy) involving heart, kidneys, spinal ganglia and peripheral nerves, spleen, pancreas, liver and vascular involvement of other organs." (PMID 20142933, 2008). "In a cohort of 235 patients with symptomatic ATTRv amyloidosis, 46 TTR mutations were identified." (PMID 40898332, 2025). "Acoramidis (AG10) represents a newer approach to TTR stabilization, mimicking the structural stabilizing properties of the TTR variant p.T139M, which protects against familial amyloid polyneuropathy in heterozygous carriers of the disease-causing p.V50M variant." (PMID 40283481, 2025). "The known prevalence of ATTRv amyloidosis in Romania is 1.02 per million (0.76 per million for the ATTRGlu54Gln mutation), and in Suceava county, it is 2.39 per 100,000 inhabitants for the same TTR mutation." (PMID 40507496, 2025). "Variants in TTR have been associated with autosomal dominant hereditary TTR amyloidosis." (PMID 41296379, 2025). "The phenotypic presentation of ATTRv amyloidosis is clinically heterogeneous, with phenotypes ranging from predominantly neurologic to predominantly cardiac to mixed, depending on the particular TTR variant and other factors such as age of onset, disease penetrance, and geographic location." (PMID 38241252, 2024). "First described in Portugal, in 1952, hereditary transthyretin-related amyloidosis (ATTRv amyloidosis—formerly “Familial Amyloid Polyneuropathy”) is a fatal, progressive, autosomal-dominant disorder caused by variants in the transthyretin (TTR) gene." (PMID 38907862, 2024). "Over 130 different TTR variants associated with ATTRv amyloidosis have been identified." (PMID 38241252, 2024). "The median overall survival of untreated patients with ATTR-CA is estimated around 3–5 years following diagnosis, with significant differences in ATTRv amyloidosis according to the specific TTR variant: overall 4-year survival of 16% in V122I, 40% in T60A and 79% in V30M." (PMID 35929637, 2023). "Predictive genetic testing offered to family members of known disease carriers allows the determination of whether an individual has pathogenic TTR mutations and is at risk of developing ATTRv amyloidosis." (PMID 37828588, 2023). "Transthyretin amyloidosis with peripheral neuropathy, also called transthyretin-related hereditary amyloidosis with peripheral neuropathy, familial amyloid polyneuropathy or Corino de Andrade disease, is an inherited neuropathy, with > 130 pathological variants identified in the TTR gene." (PMID 37059440, 2023).